PTPN6 (protein tyrosine phosphatase non-receptor type 6)
Diseases named in the same sentence as PTPN6 in open-access papers (continued):
Sharing a sentence is not in itself a finding about the gene and the disease.
bladder cancer (5 papers, 2020 to 2023). "Our observations were in line with previous research that demonstrated the association of PTPN6 with poor prognosis in patients with bladder cancer and myelodysplastic syndromes and its potential role as a tumor suppressor in esophagus cancer." (PMID 37737713, 2023). "Nevertheless, the findings of this investigation revealed that PTPN6 expression was dramatically downregulated in individuals with bladder cancer." (PMID 36211821, 2022). "However, the role of PTPN6 in bladder cancer (BC) remains unclear." (PMID 32454905, 2020). "While PTPN6 has been extensively studied in other cancer types, such as bladder cancer and colorectal cancer, its roles in GBM have not been thoroughly explored." (PMID 37737713, 2023).
chronic myelogenous leukemia (5 papers, 2018 to 2024). "It has been reported that PTPN6 mediated autophagy contributes to the inhibition of macrophage foam cell formation by the D3-VDR-PTPN6 axis, and participates in the epigenetic regulation mechanism of advanced chronic myeloid leukemia." (PMID 35095774, 2021). "Although LBH589 induces SHP-1 expression in chronic myeloid leukemia, HDAC does not directly combine with the PTPN6 promoter." (PMID 38203502, 2023).
colorectal cancer (5 papers, 2022 to 2024). A primary or metastatic malignant neoplasm that affects the colon or rectum. "PtPN6 knockdown inhibited the proliferation, invasion, migration, and clonogenesis of colorectal cancer LOVO and SW480 cells." (PMID 35186080, 2022). "Previous research has shown that PTPN6 may promote chemosensitivity in colorectal cancer cells by inhibiting the SP1/MAPK signaling pathway and enhancing macrophage effector function to bolster antitumor immunity." (PMID 37737713, 2023). "Besides, the shifted splicing pattern of ITIH5 has been introduced to prognosticate the occurrence of colorectal cancers, while the altered spicing of PTPN6 was involved in leukemogenesis." (PMID 34986865, 2022). "Moreover, PTPN6 also facilitates chemosensitivity of colorectal cancer cells by inhibiting specificity protein 1 (SP1)/MAPK signaling pathway." (PMID 35957898, 2022). "At the same time, the knockdown of PTPN6 inhibited the EMT process in colorectal cancer." (PMID 35186080, 2022).
autoimmune disease (4 papers, 2015 to 2024). A disorder resulting from loss of function or tissue destruction of an organ or multiple organs, arising from humoral or cellular immune responses of the individual to their own tissue constituents. "Mutation of PTPN6 has been linked with autoinflammatory and autoimmune diseases, and phosphorylation of MyD88 is a prerequisite for the induction of inflammatory disease in PTPN6-mutated mice." (PMID 32365080, 2020). "Consistent with this, mouse models with spontaneous mutations in the gene encoding Shp1, Ptpn6, that affect its expression or function develop an inflammatory/autoimmune disease associated with hyperactivation of multiple types of immune cells." (PMID 33133093, 2020).
Autoimmunity (4 papers, 2014 to 2024). The occurrence of an immune reaction against the organism's own cells or tissues. "PTPN6 deficiency in B cells and DC cells promotes B-1a cell development and Th1 cell differentiation, respectively, leading to autoimmune disorders." (PMID 35957898, 2022). "Suppression of IRAK1 catalytic activity has been shown to prevent LN in mice, whereas PTPN6 ablation promotes Th1 cell differentiation and induces autoimmunity." (PMID 38912505, 2024). "PTPN6, another phosphatase of PTPs, specially expressed in the cytoplasm and prevented excessive autoimmunity in IL-1 dependent inflammatory diseases and pyroptosis dependent inflammatory diseases." (PMID 36212153, 2022). "Here, the main focus is on the regulatory mechanisms by which PTPN2 and PTPN6 can be involved in autoimmunity." (PMID 35957898, 2022). "Studies of mice with a T-cell specific Ptpn6 deletion indicate that loss of Ptpn6 in T cells does not lead to overt autoimmunity, nor does it affect the number of memory precursor cells." (PMID 25147952, 2014). "The view of PTPN6 as an overall negative regulator of TCR signaling has been based mostly on studies of the motheaten mouse, which is deficient in Ptpn6 and suffers from severe autoimmunity." (PMID 25147952, 2014).
diffuse large B-cell lymphoma (4 papers, 2015 to 2024). "It has been noted that diffuse large B-cell lymphomas are prevented from progressing by the hypermethylation of the PTPN6 and PTPN13 promoters." (PMID 36699453, 2022). "Promoter hypermethylation of PTPN6 and PTPN13 was reported to inhibit the progression of diffuse large B cell lymphomas." (PMID 32536826, 2020).
Insulin resistance (4 papers, 2020 to 2025). Increased resistance towards insulin, that is, diminished effectiveness of insulin in reducing blood glucose levels. "Deletion of hepatocytic PTPN6 protects mice from hepatic insulin resistance caused by a high-fat diet (HFD) and severe liver inflammation in steatosis; however, how the role of PTPN6 in adipocytes is associated with metabolic functions remains unclear." (PMID 35563411, 2022). "Insulin-sensitive and insulin-resistant states are mediated by tyrosine protein phosphatase nonreceptor type 6 protein (PTPN6), and reducing PTPN6 expression can modulate immune system dysfunction and insulin resistance caused by hyperinsulinemia." (PMID 41020854, 2025). "Several protein tyrosine phosphatases (PTPs), particularly PTPN1, PTPN2, PTPN6, PTPN9, PTPN11, PTPRS, and DUSP9, are involved in insulin resistance." (PMID 37374154, 2023). "Since PTPs relevant to insulin resistance are promising antidiabetic targets, the identification of PTPN2 and PTPN6 inhibitors could be an effective strategy for treating or preventing type 2 diabetes." (PMID 37374154, 2023).
multiple myeloma (4 papers, 2018 to 2024). "Hypermethylation of PTPN6 is frequently seen in acute lymphoblastic leukaemia, multiple myeloma and mantle cell and follicular lymphomas, resulting in the loss of PTPN6 protein expression." (PMID 38334623, 2024). "Promoter methylation of PTPN6 leads to a very low level of expression of this protein, representing a tumor suppressor candidate in other hematological cancers, such as in multiple myeloma (MM)." (PMID 38534772, 2024). "Besides, PTPN6 was upregulated in the coculture system which consists of primary myeloma and healthy donor hematopoietic bone marrow, indicating that PTPN6 plays an important role in microenvironment interactions." (PMID 35095774, 2021).
nasopharyngeal carcinoma (4 papers, 2021 to 2024). A carcinoma arising from the nasopharyngeal epithelium. "In nasopharyngeal carcinoma (NPC), PTPN6 potentiates radioresistance and restrains cellular senescence." (PMID 35957898, 2022). "We examined the expression of BTK, CD72, PTPN6, and VAV1 in NPC cell lines by qRT-PCR, and the expression levels of BTK, CD72, PTPN6, and VAV11 were lower in human nasopharyngeal carcinoma SUNE-1 cells compared with human nasopharyngeal epithelial cells NP69 (P<0.05)." (PMID 35957889, 2022).
pancreatic cancer (4 papers, 2015 to 2022). "In our study, the PTPN6 expression in normal tissues is lower when compared to pancreatic tumor tissues." (PMID 35154122, 2022). "In this study, we found that PTPN6 can act as a biomarker that suppresses the tumorigenesis of pancreatic cancer, predict OS, and influence immune cell infiltration to alter tumor status." (PMID 34654352, 2021). "In addition, PTPN6 has been reported to control cell proliferation and determine the therapeutic potential of somatostatin in pancreatic cancer." (PMID 34654352, 2021). "Prognostic signature containing four IRGs (ADA2, TLR1, PTPN6, S100P) was constructed with good predictive performance; in particular, S100P played a significant role in the immune microenvironment, and tumorigenesis of pancreatic cancer." (PMID 34654352, 2021). "In this study, we constructed an immune-related prognostic signature based on four immune-related genes (ADA2, TLR1, PTPN6, and S100P) that displayed good predictive ability for overall survival and analyzed the infiltration of corresponding immune cells in patients with pancreatic cancer." (PMID 34654352, 2021). "Pathway analysis of its target genes via DAVID showed enrichment (FDR < 5 %) of genes in the Jak-Stat signaling pathway, including several receptors of interleukins (PTPN6, IL22RA1, CREBBP, IL28RA, IL15RA, PIK3R5, STAT3) and pancreatic cancer pathways (VEGFC, ACVR1B, PIK3R5, EGF, STAT3)." (PMID 26572553, 2015).
Alzheimer disease (3 papers, 2018 to 2025). A progressive, neurodegenerative disease characterized by loss of function and death of nerve cells in several areas of the brain leading to loss of cognitive function such as memory and language. "Moreover, among the genes that were modulated by exposure to METH, Lcn2 is involved in lipid metabolism, inflammation, iron transport and infections and Ptpn6, a protein tyrosine phosphatase, that is involved in adaptive and innate immunity and has been linked to Alzheimer’s Disease as risk factor." (PMID 40143289, 2025).
cervical cancer (3 papers, 2020 to 2024). A primary or metastatic malignant neoplasm involving the cervix. "PTPN6 is positively correlated with HPV infection in cervical cancer with the explanation of cell defense reaction." (PMID 33671013, 2021). "From this IRG–TF regulatory network, we can see that in cervical cancer, FOXP3 positively regulates low-risk IRGs (LTA and PTPN6) and positively regulates low-risk IRGs (LTA) in endometrial cancer, suggesting that FOXP3 may act as a tumor suppressor in these two types of cancers." (PMID 32793281, 2020).
COVID-19 (3 papers, 2021 to 2025). A disease caused by infection with severe acute respiratory syndrome coronavirus 2. "Moreover, we find evidence linking PTPN6 to a range of comorbidities along with the genetic predisposition of COVID-19, suggesting that this kinase is a central player in severe cases of COVID-19." (PMID 35903362, 2022). "GNB1 showed the largest increase in the plasma of PLWH with COVID-19, followed by PTPN6, FERMT3, and PSTPIP2." (PMID 40568587, 2025). "BCR inhibitory gene expression was limited, but CD22 was detectable across B cell subsets in asymptomatic COVID-19, while FCGR2B, CD72 and PTPN6 expression was evident in B cells in severe COVID-19." (PMID 33879890, 2021). "Protein tyrosine phosphatase non-receptor type 6 (PTPN6) was associated with one COVID-19 node and with the highest number of diseases from COPD over hypertension to cerebrovascular disease." (PMID 35903362, 2022).
diabetes (3 papers, 2022 to 2024). "This study highlights QG as a potent and novel compound against diabetes that targets both PTPN6 and PTPN9." (PMID 38474775, 2024). "In this study, we identified PTPN6 as a potential target against both diabetes and obesity using siRNA." (PMID 35563411, 2022). "QG was recognized as a dual-target drug compound with an inhibitory effect against PTPN6 and PTPN9, presenting a potential treatment for diabetes in muscle cells." (PMID 38474775, 2024). "Genes co-expressed with PTPN6 were correlated with “Immune response_T cell co-signaling receptors, schema”, “Breakdown of CD4+ T cell peripheral tolerance in type 1 diabetes mellitus”, and “Chemotaxis_SDF-1/CXCR4-induced chemotaxis of immune cells”." (PMID 36556168, 2022).
emphysema (3 papers, 2017 to 2025). "When emphysema was identified, the PTPN6 gene was sequenced and alpha1antitrypsin deficiency searched." (PMID 41194194, 2025). "When emphysema was identified, the PTPN6 gene was sequenced using Sanger method (ABI Prism 3730XL Genetic Analyzer; Applied Biosystems®) and alpha-1-antitrypsin (AAT) deficiency was searched (serum level, isoelectric focusing and gene sequencing)." (PMID 41194194, 2025). "Our results suggest that Al2O3 NPs exposure induces emphysema and airway remodeling in murine lungs by suppressing PTPN6 expression and enhancing inflammation." (PMID 29233151, 2017). "The mice were also protected from emphysema and airway remodeling by PTPN6 overexpression." (PMID 29233151, 2017). "Thus, PTPN6-overexpression protects against emphysema and small airway remodelling, highlighting the functional role of PTPN6 in Al2O3 NPs-induced lung injury associated with COPD-like effects." (PMID 29233151, 2017). "We hypothesize that as a consequence of suppressed expression of PTPN6, STAT3 activation and PDCD4 expression increase in airway and alveolar epithelial cells, leading to apoptosis, inflammation and emphysema in experimental COPD." (PMID 29233151, 2017).
endometrial cancer (3 papers, 2020 to 2024). Primary or metastatic malignant neoplasm involving the endometrium (mucous membrane that lines the endometrial cavity). "In CPTAC data, PTPN6 was expressed at significantly higher levels in endometrial cancer compared to normal tissue." (PMID 35887124, 2022).
lung carcinoma (3 papers, 2022 to 2025). "The antitumor functions of FYN, SYK, and PTPN6 in lung cancer have been validated by previous research, which was consistent with our study." (PMID 37279937, 2023). "To further verify the role of these prognostic genes in AML, we performed in vitro experiments on PTPN6 and CSK which their cellular effects in lung cancer are unclear." (PMID 40255396, 2025).
melanoma (3 papers, 2020 to 2022). A malignant, usually aggressive tumor composed of atypical, neoplastic melanocytes. "Knocking down Ptpn6 with shRNA leads to enhanced antigen uptake and priming of T cells, and enhanced activity in an in vivo vaccination model of B16F10 melanoma." (PMID 33133093, 2020). "However, another study showed that Ptpn6 knockdown did not promote anti‐tumor immunity against B16 melanoma by transgenic T cells, unless checkpoint blockade was administered, raising questions on the conditions in which PTPN6 is relevant for antitumor T cell immunity." (PMID 36194675, 2022).
myelodysplastic syndrome (3 papers, 2022 to 2024). A clonal hematopoietic disorder characterized by dysplasia and ineffective hematopoiesis in one or more of the hematopoietic cell lines. "It suggests that the PTPN6 gene acts as a tumor suppressor in myelodysplastic syndrome cells, influencing hematopoietic cell apoptosis, erythroid differentiation, and inflammations." (PMID 39590309, 2024). "In order to investigate the role of PTPN6 in hematologic tumor myelodysplastic syndrome (MDS), this study infected SKM-1 cell line (MDS cell line) with packaged H_PTPN6-shRNA lentivirus to obtain H_PTPN6-shRNA SKM-1 stable strain." (PMID 39590309, 2024).
neuroblastoma (3 papers, 2020 to 2024). Neuroblastoma (NB) is the most common solid, extracranial childhood tumor. "This is in accordance with the association found between good patient prognosis and PTPN6 low expression and tyrosine phosphorylated TrkA (Tyr674/675) expression in neuroblastoma tumors." (PMID 34957126, 2021). "Previous studies have also shown that PTPN6 can serve as a prognostic factor in cancers, such as neuroblastoma and peripheral T cell lymphomas." (PMID 32454905, 2020).
Obesity (3 papers, 2015 to 2022). Accumulation of substantial excess body fat. "Since AMPK is activated after the knockdown of PTPN6, PTPN6 was also evaluated as a target for obesity using siRNA." (PMID 35563411, 2022). "In an approach to discover new compounds with anti-diabetic or anti-obesity effects, natural products inhibiting PTPN6 were searched from an in-house library." (PMID 35563411, 2022). "PTPN6 is reported to show high expression in insulin target tissues in obesity, in which it interacts with P85, resulting in P85 dephosphorylation and reduced AKT phosphorylation in the control of liver metabolism; however, the mechanism is unclear." (PMID 33901186, 2021). "Collectively, compounds that inhibit PTPN6 and antagonize PPARγ are believed to exhibit potential effects on T2DM and obesity." (PMID 35563411, 2022). "When we investigated the list of 162 DMRs mapping to annotated loci in further detail we observed other genes with known and potential roles in obesity and related traits (such as PRKCZ, NDUFS2, GATA2, FOXP2, ANGPT2, NCOR2, CPT1B, PTPN6)." (PMID 25651499, 2015).
primary immunodeficiency (3 papers, 2021 to 2024). "PTPN6 was enriched in arachidonic acid metabolism, the B cell receptor signaling pathway, glycosylphosphatidylinositol (GPI) anchor biosynthesis, neuroactive ligand–receptor interaction, primary immunodeficiency, and proteasomes." (PMID 38919950, 2024).
amyloid (2 papers, 2018 to 2024). "Specifically, we find that the interaction of CD33 and PTPN6 modulates the association with amyloid burden, tangles, pathological diagnosis of AD, and global burden of AD pathology." (PMID 39336795, 2024). "Interestingly, not only do we observe robust SYK upregulation around amyloid plaques (> 3-fold) but associated protein tyrosine phosphatases PTPN6 and INPP5D are also enriched (upregulated 6.0-fold and 2.7-fold respectively)." (PMID 30189875, 2018).
atherosclerosis (2 papers, 2016 to 2020). A disease characterized by the build-up of fatty material and calcium deposition in the arterial wall resulting in partial or complete occlusion of the arterial lumen. "However, here we found PTPN6 up-regulated in atheroma at both the mRNA and proteins level and for the first time linked PTPN6 to atherosclerosis." (PMID 26742467, 2016). "This study identified SYK, LYN, PTPN6 and the “FcεRI-mediated signaling pathway” as potential candidate players involved in the pathogenesis of atherosclerosis." (PMID 26742467, 2016). "The analysis revealed that a similar representation of the gene expression patterns of our candidate DEGs was seen in the dataset GSE28829, suggesting that VAV1, SYK, LYN and PTPN6 genes may play an important role in progression of atherosclerosis." (PMID 26742467, 2016).
B-cell lymphoma (2 papers, 2021 to 2024). "PTPN6 acts as a negative regulator of immune responses by hydrolyzing PIP3, and its deficiency leads to bone marrow proliferation and B-cell lymphoma in mice." (PMID 39590309, 2024). "For B-cell lymphoma only three genes are found in cosmic (CD22, MDN1, and PlCG2) and three genes (CD22, PTPN6, PLCG2) are oncogenes." (PMID 34570764, 2021).
depression (2 papers, 2024 to 2025). "Additionally, PTPN6, STIP1, ANPEP, and TSPYL1 were found to be correlated with major depressive disorder." (PMID 40520536, 2025).
esophageal cancer (2 papers, 2022 to 2023). A primary or metastatic malignant neoplasm involving the esophagus. "Interestingly, PTPN1 expression is implicated in the incidence of esophageal cancer, while PTPN6 is down-regulated in esophageal cancer and PTPN12 is a favorable prognostic biomarker for patients with esophageal squamous cell carcinoma." (PMID 35957898, 2022).
glioblastoma (2 papers, 2023 to 2026). The most malignant astrocytic tumor (WHO grade IV). "To further elucidate the role of PTPN6 in glioblastoma development, we investigated immune cell infiltration in C57BL/6 mice." (PMID 37737713, 2023). "Our results demonstrated that mouse glioblastoma cells stably expressing PTPN6 significantly increased tumor development." (PMID 37737713, 2023). "Background/Objectives: Src homology 2 domain-containing protein tyrosine phosphatase 1 (SHP-1), also known as protein tyrosine phosphatase non-receptor type 6, functions as a tumor suppressor in breast, hepatocellular, and prostate cancers and an oncogene in glioblastoma and cervical cancer." (PMID 42122197, 2026).